CERK (ceramide kinase)
Diseases named in the same sentence as CERK in open-access papers (continued):
Sharing a sentence is not in itself a finding about the gene and the disease.
lung diseases (1 paper, 2014). "Furthermore, the dysregulated migratory and proliferative phenotypes observed in the CERK-null fibroblasts is quite similar to the phenotype of fibroblasts isolated from the fibrotic lung diseases." (PMID 24823941, 2014).
migraine (1 paper, 2025). "Subsequently, increased CerK activity in patients with migraine could explain the low levels of Cer detected despite the increase in aSMase activity both in our and in previous works." (PMID 40002346, 2025).
nonalcoholic fatty liver disease (1 paper, 2025). "Moreover, oral administration of the sphingosine analog FTY720, which upregulates CerK and is used for the treatment of multiple sclerosis, also ameliorates Alzheimer ́s disease and steatosis in a model of nonalcoholic fatty liver disease." (PMID 40653199, 2025).
osteoarthritis (1 paper, 2024). A noninflammatory degenerative joint disease occurring chiefly in older persons, characterized by degeneration of the articular cartilage, hypertrophy of bone at the margins and changes in the synovial membrane. "Ultimately, 4 hub genes (UGCG, ESYT1, PTGS2, and CERK) were identified as vital players in osteoarthritis lipid metabolism." (PMID 38637751, 2024). "After synthesizing three machine learning algorithms, Lasso regression, SVM-RFE, and random forest, four hub genes of osteoarthritis lipid metabolism were further screened: UGCG, ESYT1, PTGS2, and CERK." (PMID 38637751, 2024).
retinal disease (1 paper, 2021). "Diseases related to CERK include retinitis pigmentosa disease, a retinal disease causing degeneration of photoreceptors in humans." (PMID 33152221, 2021).
triple-negative breast carcinoma (1 paper, 2023). An invasive breast carcinoma which is negative for expression of estrogen receptor (ER), progesterone receptor (PR), and human epidermal growth factor receptor 2 (HER2). "It is worth noting that CERK has become a common therapeutic target for triple positive and triple negative breast cancer cells." (PMID 37305043, 2023). "In triple negative breast cancer, the up regulation of CERK is significantly related to its chemoresistance, which may be mediated by the up regulation of Ras/ERK and PI3K/Akt pathways." (PMID 37305043, 2023).
cancer (28 papers, 2008 to 2025). A tumor composed of atypical neoplastic, often pleomorphic cells that invade other tissues. "High levels of SPHK1 and CERK in nodal positive and late-stage cancer patients as well as association of high CERK expression to poor patient survival are indicative of their potential as diagnostic and prognostic biomarkers." (PMID 36309544, 2022). "As the only enzyme known to generate C1P, CERK has also been implicated in cancer cell growth, survival, inflammation, and dissemination." (PMID 33430896, 2021). "The results obtained reveal that CerK protein expression and the Ceramide/C1P axis are markedly impaired in all experimental models, demonstrating that the CerK/C1P axis plays a crucial role as molecular regulator of SkM mass associated to cancer or corticosteroids." (PMID 34209043, 2021). "Altogether, these findings provide evidence that CerK, acting as a molecular modulator, may be a new possible target for SkM mass regulation associated with cancer or corticosteroids." (PMID 34209043, 2021). "Although C1P in certain scenarios acts as an anti-inflammatory molecule, but in most part, it is speculated that CERK may be a target for a new anti-inflammatory drug and probably for inflammation-associated cancer." (PMID 29269995, 2017). "The mechanisms underlying the role of CERK role in cancer are still largely unknown." (PMID 33430896, 2021). "Ceramide kinase (CERK) is a sphingolipid metabolic enzyme that can phosphorylate intracellular ceramide and, hence, promote cancer cell growth." (PMID 39126035, 2024). "Cer1P arises from the phosphorylation of ceramide by ceramide kinase (CERK) and is a known regulator of cell survival and proliferation in a variety of cell types, including cancer cells." (PMID 37373053, 2023). "Bile acid, namely LCA, activated cancer-promoting genes including Cers1, Cers2, Cers5, and CERK in the cancerous HT-29 cell line in a miR125b-dependent way." (PMID 37298127, 2023). "The activation of conduction factor CERK indirectly triggers dysregulation of the immune response, cancer cell proliferation, and metastasis by upregulating TF MYBL2 to overexpress." (PMID 35164166, 2022). "CERK and its product, ceramide 1-phosphate (C1P), regulate cell growth, death, and cell migration/invasion in different cancers, including PCa." (PMID 35740569, 2022). "The present review provides an updated view on the important role of CERK/C1P in the regulation of cancer cell growth, survival, and dissemination." (PMID 35008391, 2022). "CERK-produced intracellular C1P has been shown to be required for invasion/migration of a variety of cancer cell types." (PMID 35008391, 2022). "Taking into consideration the topology or compartmentalization of C1P in cancer cells, the therapeutic relevance of CERK and C1P can be pursued at two different levels." (PMID 35008391, 2022). "CerK is ubiquitously expressed in various mammalian tissues and its importance only recently started to be appreciated in cancer as well as in other pathological states, such as those characterized by inflammation." (PMID 34209043, 2021). "We and others have previously shown that the product of CERK, C1P, promotes cancer cell aggressiveness in other cellular systems." (PMID 34503116, 2021). "The results obtained reveal that CerK protein expression is markedly reduced in all experimental models of cancer-induced atrophy, demonstrating that the CerK/C1P axis plays a role of molecular regulator of SkM mass in these conditions." (PMID 34209043, 2021). "We previously suggested a prominent role of CerK in cell cycle and mitosis regulation in cancer cells." (PMID 32092937, 2020). "Following this study many research supported the fact that CERK/C1P is an important component of survival signaling for cancer progression." (PMID 29269995, 2017). "1,25-Dihydroxyvitamin D3 has been shown to potently inhibit CERK activity, thus reducing cancer cell growth, again indicating that CERK is a survival kinase for cancer cells." (PMID 29269995, 2017).
cancer (continued). "It appears that like S1P, CERK/C1P is also involved in proinflammatory signaling and cancer progression." (PMID 29269995, 2017). "The fact that C1P is a strong activator of cPLA2 places CERK as a new potential therapeutic target for cancer treatment and/or prevention." (PMID 21566746, 2008). "Similarly, CERK/C1P pathway plays a prominent role in regulating the growth, survival and spread of cancer cells." (PMID 37305043, 2023). "Very recently, CERK has also been identified from an inhibitor screen as a potent target to reduce chemotherapy induced senescent cell population that promotes inflammation and reduces the effectiveness of chemotherapy on cancer cells." (PMID 36139656, 2022). "Furthermore, CERK activity and its metabolites support cancer progression, particularly PCa cell aggressiveness." (PMID 35740569, 2022). "In summary, distinct sphingolipid profiles of TPBC and TNBC representing cell lines provide potential therapeutic targets such as CERK, and nanoparticle/hydrogel mediated pharmacological manipulations of such targets can be explored for future cancer therapeutics." (PMID 36139656, 2022). "The biology of CERK/C1P in cancer growth and dissemination is herein discussed in detail." (PMID 35008391, 2022). "However, no report has so far compiled or put into context the information related to the implication of the CERK/C1P axis in cancer development and metastasis." (PMID 35008391, 2022). "Therefore, CERK emerges as a potential therapeutic target that can be explored further for cancer therapy." (PMID 36139656, 2022). "Taken together, these findings suggest that the regulatory role of CERK in migration might be cancer-cell type specific." (PMID 33430896, 2021). "Increased activity of enzymes catalysing pro-malignant sphingolipids formation reactions, such as glutamate-cysteine ligase (GCL), spermine synthase (SMS), sphingosine kinase (SphK) and ceramide kinase (CERK) results in the apoptosis escape and cancer progression." (PMID 32715369, 2020). "We found that the gene expression of CERK was significantly suppressed in cancer." (PMID 29731990, 2018). "ATRA inhibited transcriptional activity of CERK via regulation of a COUP-TF1 transcription factor, indicating that CERK/C1P might be an important lipid signaling molecule for cancer cell survival." (PMID 29269995, 2017). "Also, safingol (L-threo-dihydrosphingosine), a potent sphingosine kinase (SK) inhibitor, is commonly used in cancer therapy to avoid formation of S1P, and the recently identified inhibitor of ceramide kinase, F-1209A, can be used to inhibit C1P generation." (PMID 21566746, 2008). "In the light of the pro-survival and pro-inflammatory functions of C1P, CERK, the enzyme responsible for C1P formation, might be an important target for the development of novel anti-cancer drugs." (PMID 21566746, 2008). "Moreover, CerK inhibition suppressed growth and induced apoptosis in cisplatin-resistant ovarian cancer cells, thereby enhancing the efficacy of cisplatin as chemotherapeutic agent in this type of cancer." (PMID 40943293, 2025). "Although the putative C1P receptor(s) is (are) still to be fully characterized and cloned, these, together with CERK, may be highly relevant to promote the development of a new generation of cancer metabolism-targeting agents to aid in the prevention or cure of cancer." (PMID 35008391, 2022). "However, despite these observations, the contribution of both CerK and the Cer/C1P axis to muscle wasting associated to cancer and to corticosteroid response is not sufficiently explored." (PMID 34209043, 2021). "Therefore, the negative regulation of CerK expression may contribute to the cancer-induced SkM atrophy in vivo, potentially acting on both differentiated myofibers and SkM progenitor cells." (PMID 34209043, 2021).
cancer (continued). "Indeed, MCF-7 cells showed much lower CerK mRNA and CerK activity, thus further supporting the hypothesis that CerK expression correlates with the metastatic potential of cancer cells." (PMID 32092937, 2020). "CERK functions in the survival maintenance of KRAS-mutant NSCLC CERK regulates mitochondrial membrane potential (MMP) and reduces ROS levels in cancer cells." (PMID 40959280, 2025). "In cancer cells, SGMS activity keeps low levels of ceramide; moreover, ceramide 1-phosphate (produced by CERK-dependent phosphorylation of ceramide) plays an important role in cell proliferation and migration and in cancer aggressiveness." (PMID 36674430, 2023). "Since choline synthesis is a crucial event for cancer cells, MALAT1 targeting downregulates CHKA and CERK activity; this effect seems to overlap the activity of CHKA inhibitors." (PMID 36674430, 2023). "Past few studies have demonstrated that CERK activation and intracellular C1P are involved in noncancer and cancer cell growth and survival." (PMID 29269995, 2017). "However, in tumors of the SLURP-1-treated mice, we observed a significant increase in expression of the genes coding α7-nAChR (CHRNA7), pro-oncogenic integrin α5 (ITGA5), and ceramide kinase (CERK), which are responsible for growth and migration of cancer cells." (PMID 37854069, 2023). "In addition, mRNAs for two of the three enzymes that also utilize Cer for biosynthesis of other sphingolipids (sphingomyelin synthase 1, SMS1, and ceramide kinase, CERK) and the Cer transport protein CERT appear to be lower for the carcinoma cells versus normal stromal tissue." (PMID 20624317, 2010).
tumor (19 papers, 2015 to 2025). "A > 2-fold change in CERK (from tumor)/CERK (from normal counterpart) was significantly associated with chemo-resistance (OR = 2.66, 95% CI 1.18–7.34), P = 0.04." (PMID 33430896, 2021). "At the same time, a significant decrease in cell migration in MDA-MB-231 cells and alleviation of growth in the xenograft tumor model implicated that CERK downregulation is equally important for primary tumor abrogation and migration of disseminated tumor cells in TNBC cells." (PMID 36139656, 2022). "Therefore, one could hypothesise that a decrease in ceramide level due to acid sphingomyelinase deficiency with conserved SHPK and ceramide kinase activities would lead to an imbalance in favour of S1P and C1P and a subsequent pro-tumour effect." (PMID 34768550, 2021). "YAP phosphorylation and activation of the sphingolipid metabolic enzyme SGPP2 jointly mediate tumor metabolic adaptation; whilst the sphingolipid metabolic enzyme CERK promotes drug resistance in ER+ BC." (PMID 41415282, 2025). "An overview of the gene and sphingometabolic profiles of TPBC and TNBC cells suggest CERK as an apt target to combat tumor cell proliferation and migration in both subtypes." (PMID 36139656, 2022). "Localized delivery of these polyplexes with CERK siRNA reduced the tumor growth kinetics, making it a potential candidate for future gene therapy applications." (PMID 36139656, 2022). "In the present study, protein expression of both SPHK1 (*p = 0.041) and CERK (**p = 0.0028) were found to be significantly upregulated in tumor tissue as compared to adjacent normal tissue." (PMID 36309544, 2022). "Our results showed that this lithocholic acid-derived hydrogel implant can also encapsulate CERK inhibitor, and its implantation near the tumor site can reduce tumor progression." (PMID 36139656, 2022). "We showed a striking decrease in luminal specific BT-474 cell proliferation and a significant tumor regression in corresponding xenograft model on CERK inhibition." (PMID 36139656, 2022). "In the first strategy, we used nanoparticle-mediated delivery of siRNA targeting CERK to tumor tissues, and in the second strategy, we used hydrogel-mediated localized delivery of CERK inhibitor near the tumor site, and determined their effect on tumor growth." (PMID 36139656, 2022). "Tumor growth kinetics showed that siRNA-mediated knockdown of CERK inhibited the BT-474 tumor growth as compared to other groups, and there was a >2.5-fold (p < 0.0001) decrease in tumor volume on final day." (PMID 36139656, 2022). "Consistent with the previous findings, increased protein expression of CERK was observed in tumor tissues as compared to adjacent normal tissues." (PMID 36309544, 2022). "Overexpression of CERK and SPHK1 was associated with nodal metastasis, late tumor stage and high proliferation potency." (PMID 36309544, 2022). "On one hand, as CERK is responsible for the generation of intracellular C1P, targeting this enzyme activity or expression is an exciting strategy to curb tumor growth." (PMID 35008391, 2022). "We further demonstrated that nanoparticle/hydrogel mediated inhibition of CERK using siRNA or chemical inhibitor can be an effective strategy to mitigate cell proliferation and tumor progression in these subtypes." (PMID 36139656, 2022). "It is interesting to note that the upregulation of CERK expression (tumor/normal > 2) is found only in some TNBC patients, with a significant association with chemoresistance." (PMID 33430896, 2021). "We first investigated the expression of CERK in paired TNBC tumor and adjacent normal breast tissue obtained from one hundred TNBC patients who has not received treatment as of yet." (PMID 33430896, 2021). "We next performed a retrospective analysis of the influence of CERK tumor/normal ratio on chemotherapeutic response in TNBC patients." (PMID 33430896, 2021).
tumor (continued). "We showed that the CERK mRNA level varied remarkably in both TNBC tumor and normal breast tissue, with the average higher in tumor tissue than in normal tissue." (PMID 33430896, 2021). "The present study reports significantly high levels of CERK in tumor tissues as compared to adjacent normal tissues in local as well as TCGA cohort." (PMID 32170160, 2020). "There was a significant increase in the levels of Ceramide Kinase (CERK) gene in tumor tissues as compared to adjacent normal tissues in both local as well as TCGA cohort." (PMID 32170160, 2020). "Given that LCA, an established tumour promoter, has been implicated in CRC metastasis and is primarily presented within the colon, we examined the expression of Cers1, Cers2, Cers5, and CERK in LCA-stimulated human intestinal epithelial cells." (PMID 37298127, 2023). "In addition, nanoparticle mediated CERK siRNA delivery and hydrogel mediated continuous delivery of CERK inhibitors to tumor sites can also inhibit tumor progression." (PMID 37305043, 2023). "Hence, the present review highlights the relevance of CERK and C1P in tumorigenesis and tumor dissemination." (PMID 35008391, 2022). "We validated the knockdown of CERK in tumor tissues by immunoblotting." (PMID 36139656, 2022). "We also showed that the targeting of CERK at transcriptional level by siRNA therapeutics or inhibiting the CERK activity by hydrogel-mediated delivery of chemical inhibitors can be an effective strategy to slow down the tumor progression." (PMID 36139656, 2022). "Accordingly, CERK overexpression showed to be a biomarker for chemotherapeutic response in TNBC and higher than two-fold change in CERK (from tumor)/CERK (from normal counterpart) ratio was significantly linked to chemoresistance to doxorubicin and paclitaxel (OR = 2.66, 95% CI 1.18–7.34), p = 0.04." (PMID 35163586, 2022). "Therefore, we used two strategies to evaluate the effect of pharmacological manipulations of CERK on tumor progression." (PMID 36139656, 2022). "Although the molecular mechanisms whereby CERK/C1P exerts its biological functions are still incomplete, accumulating evidence supports the notion that this enzyme activity and its product are relevant targets for reducing tumor formation and spreading." (PMID 35008391, 2022). "In particular, C1P and ceramide kinase (CerK), play key roles in tumor promotion and dissemination." (PMID 34209043, 2021). "We interrogated whether the regulation of CERK by EZH2 could be a general phenomenon in this tumor type." (PMID 34503116, 2021). "Indeed, CerK inhibition promoted a striking decrease in Luminal specific BT-474 cell proliferation and a significant tumor regression in the corresponding xenograft model, sustaining the idea that CerK can potentially be a good therapeutic target for primary tumors of Luminal subtype." (PMID 36768427, 2023). "Next, we randomized the BT-474 and MDA-MB-231 tumor-bearing mice into three groups, where group 1 mice were left untreated, group 2 mice were treated with siRNASCRAM NPs with scrambled siRNA, and group 3 mice were treated with siRNACERK NPs with CERK-targeted siRNA." (PMID 36139656, 2022). "We further demonstrated that nanoparticle-mediated delivery of CERK siRNA and hydrogel-mediated sustained delivery of CERK inhibitor to the tumor site can inhibit tumor progression in BT-474 and MDA-MB-231 tumor models." (PMID 36139656, 2022). "The average level of CERK mRNA and protein in TNBC tumor tissue was approximately two-fold higher than normal." (PMID 33430896, 2021). "The AUC values for CERK and SPHK1 depicted a fair and significant potential to discriminate between tumor and adjacent normal tissues in local and TCGA cohort respectively." (PMID 32170160, 2020). "A significant upregulation in the expression of CERK and SPHK1 was observed in tumor tissues in local and TCGA cohort." (PMID 32170160, 2020).